YKT6 (YKT6 vesicular SNARE protein)
Description:
Vesicular soluble NSF attachment protein receptor (v-SNARE) mediating vesicle docking and fusion to a specific acceptor cellular compartment. Functions in endoplasmic reticulum to Golgi transport; as part of a SNARE complex composed of GOSR1, GOSR2 and STX5 (By similarity). Functions in early/recycling endosome to TGN transport; as part of a SNARE complex composed of BET1L, GOSR1 and STX5. Has a S-palmitoyl transferase activity. Essential for the structural and functional organization of the Golgi apparatus.
Tractability: Small molecule: a structure with a bound ligand is known. Antibody: its Gene Ontology location is reachable by antibodies, with high confidence. PROTAC: ubiquitination databases record sites on it; its protein half-life has been measured.
Gene: Protein-coding gene on chromosome 7 (44,200,959 to 44,214,294, forward strand). Ensembl gene ENSG00000106636.
Subcellular location: Cytoplasm, cytosol; Cytoplasmic vesicle membrane; Golgi apparatus membrane
Subcellular location (Human Protein Atlas): Cytosol; Mitochondria
Pathways (Reactome):
Signal Transduction: CDC42 GTPase cycle; RAC1 GTPase cycle; RAC3 GTPase cycle; RHOA GTPase cycle; RHOG GTPase cycle
Vesicle-mediated transport: COPI-mediated anterograde transport; COPII-mediated vesicle transport; Intra-Golgi traffic
Gene Ontology:
Molecular function: cadherin binding; protein binding; protein-cysteine S-palmitoyltransferase activity; SNAP receptor activity
Biological process: endoplasmic reticulum to Golgi vesicle-mediated transport; retrograde transport, endosome to Golgi; vesicle-mediated transport; vesicle fusion
Cellular component: cytoplasm; endoplasmic reticulum; endosome; Golgi apparatus; plasma membrane; autophagosome membrane; endoplasmic reticulum-Golgi intermediate compartment membrane; Golgi membrane; membrane fusion priming complex; SNARE complex; transport vesicle; apical dendrite; basal dendrite; cytoplasmic vesicle membrane; cytosol; membrane; neuronal cell body
Genetic constraint (gnomAD): Loss-of-function variants: 12 observed, 30.59 expected, observed/expected ratio (o/e) 0.39, 90% interval 0.25 to 0.64. The upper end of that interval is the gene's LOEUF score, 0.64, which puts it in group 2 of 6, group 1 being the genes least tolerant of losing a copy. Missense variants: 188 observed, 255.67 expected, observed/expected ratio (o/e) 0.74, 90% interval 0.65 to 0.83. Synonymous variants: 86 observed, 98.78 expected, observed/expected ratio (o/e) 0.87, 90% interval 0.73 to 1.04.
Homologues: Orthologues: chimpanzee YKT6 (100% identical), macaque YKT6 (100% identical), rat Ykt6 (95% identical), dog YKT6 (94% identical), mouse Ykt6 (93% identical), guinea pig YKT6 (92% identical), tropical clawed frog ykt6 (87% identical), zebrafish ykt6 (85% identical), pig YKT6 (73% identical), Drosophila melanogaster Ykt6 (61% identical), Caenorhabditis elegans ykt-6 (57% identical). Paralogues in human: VAMP7 (20% identical), SEC22B (19% identical), VAMP4 (16% identical), SEC22A (15% identical), VAMP1 (14% identical), SEC22C (14% identical), VAMP2 (14% identical), VAMP8 (11% identical), VAMP3 (11% identical), VAMP5 (9% identical).